TRIM49D1 (tripartite motif containing 49D1)
Synonyms: TRIM49D; TRIM49D1P; TRIM49DP
Tractability: No criterion of Open Targets' tractability assessment is met for any kind of drug.
Gene: Protein-coding gene on chromosome 11 (89,911,111 to 89,922,245, reverse strand). Ensembl gene ENSG00000223417.
Subcellular location (Human Protein Atlas): Nucleoplasm; Cytosol
Gene Ontology:
Molecular function: ubiquitin protein ligase activity; zinc ion binding
Biological process: innate immune response; regulation of gene expression
Cellular component: cytoplasm
Homologues: Paralogues in human: TRIM49D2 (100% identical), TRIM49B (85% identical), TRIM49C (85% identical), TRIM49 (85% identical), TRIM51 (74% identical), TRIM51G (70% identical), TRIM43 (51% identical), TRIM43B (50% identical), TRIM64 (44% identical), TRIM64B (44% identical), TRIM48 (44% identical), TRIM64C (43% identical), and 68 more.